SQSTM1 (sequestosome 1)
Diseases named in the same sentence as SQSTM1 in open-access papers (continued):
Sharing a sentence is not in itself a finding about the gene and the disease.
pancreatic adenocarcinoma (3 papers, 2011 to 2019). "Finally, accumulation of SQSTM1 protein correlates with loss of CDH1/E-cadherin expression in pancreatic adenocarcinoma." (PMID 30782064, 2019). "Finally, we assessed the expression of SQSTM1 and CDH1 in human pancreatic adenocarcinoma where 90% of tumors harbor KRAS mutations." (PMID 30782064, 2019). "It is possible that the high expression of Nrf2 in the pancreatic adenocarcinoma tissues is due to the elevated expression of proteins that can increase the stability of Nrf2, such as Sequestosome-1 and Prothymosin-α, by competing with Nrf2 for the Keap1 binding site." (PMID 21489257, 2011). "Our transcriptome analysis of differentially expressed genes in the pancreatic adenocarcinoma AR42J cells revealed that gastrin upregulates the mRNA level of autophagy related genes (e.g. Sqstm1 and beclin 1 (E-MTAB-1268 and GSE32869)), suggesting that gastrin may induce autophagy." (PMID 28109268, 2017).
pancreatitis (3 papers, 2014 to 2026). Inflammation of the pancreas. "Similar to the autophagy-deficient liver, increased p62/SQSTM1 levels were also found in the IKK-α-deficient pancreas, and further deletion of p62/SQSTM1 in the pancreas attenuated pancreatitis in pancreas-specific IKK-α-deficient mice." (PMID 25140315, 2014).
primary biliary cirrhosis (3 papers, 2014 to 2023). "Previous studies have found that DLAT colocalizes with autophagy markers LC3 and SQSTM1 among patients with primary biliary cirrhosis (PBC), and the autophagy induced in bile epithelial cells is related to the over-expression of DLAT." (PMID 36949759, 2023). "Moreover, the expression of p62/SQSTM1 and LC3-II also increases in livers from patients with primary biliary cirrhosis and cultured biliary epithelial cells treated with hydrogen peroxide, with an accumulation of p62-positive aggregates." (PMID 24490870, 2014).
prostate adenocarcinoma (3 papers, 2015 to 2022). "The subcellular localization and expression of AMBRA1 and SQSTM1 proteins were observed and scored by IHC on large section of prostate adenocarcinoma from 26 patients." (PMID 26423274, 2015).
pulmonary fibrosis (3 papers, 2015 to 2022). Chronic progressive interstitial lung disorder characterized by the replacement of the lung tissue by connective tissue, leading to progressive dyspnea, respiratory failure, or right heart failure. "The relevance of p62/SQSTM1 function to pulmonary fibrosis is further supported by studies describing accelerated aging and age-related pathologies associated with loss of p62/SQSTM1." (PMID 26059457, 2015). "This study shows a novel mechanism that NRF2 and SQSTM1 play fundamental roles through regulating autophagy in lung fibrosis." (PMID 34880752, 2021). "It was recently shown that autophagy inhibition-mediated EMT could augment local myofibroblast differentiation via p65/RELA-mediated transactivation of Snail2 caused by increased p62/SQSTM1 expression in pulmonary fibrosis, suggesting that autophagy could inhibit EMT to extenuate pulmonary fibrosis." (PMID 36589681, 2022). "Besides, defects in SQSTM1 may contribute to the deregulation in NRF2 activity seen in myofibroblasts and pulmonary fibrosis." (PMID 34880752, 2021). "However, the interaction of NRF2 and SQSTM1 is not confirmed in lung fibrosis." (PMID 34880752, 2021).
renal carcinoma (3 papers, 2020 to 2021). A carcinoma arising from the epithelium of the renal parenchyma or the renal pelvis. "Therefore, SQSTM1 was regarded as a pathogenic target of 5q CN gains in renal cancer." (PMID 31892969, 2020). "A key enriched candidate within these Cd aggregates is SQSTM1, a scaffold signaling protein, the accumulation of which is essential for the development of lung and renal carcinoma." (PMID 34065348, 2021). "(ii) Several seminal studies, both in vitro and in vivo, demonstrated that SQSTM1 is essential for NF-κB signaling, and thereby for cell transformation, lung, and renal cancer development." (PMID 34065348, 2021). "Copy number gains of chromosome 5q occurring in CCRCC drive overexpression of the gene SQSTM1; the p62 SQSMT1 protein is involved in activation of NRF2, and through this mechanism, in promotion of resistance to redox stress and in stimulation of renal cancer cell growth in vitro and in vivo." (PMID 32751108, 2020).
renal fibrosis (3 papers, 2022 to 2024). A final common manifestation of a wide variety of chronic kidney diseases characterized by glomerulosclerosis and tubulointerstitial fibrosis. "Furthermore, the in vivo study employed with SQSTM1 cKO mice confirmed that SQSTM1 in tubular cells played a critical role in the protective effect of Cana on renal fibrosis." (PMID 36685533, 2022). "Collectively, this study uncovered a previously unrecognized function of canagliflozin in FTO in the autophagy modulation through the regulation of SQSTM1 mRNA stability in the renal tubular STAT6/PPARα/FAO axis and renal fibrosis." (PMID 36685533, 2022). "Here, we found that canagliflozin significantly upregulates SQSTM1/P62, promoting PPARα-mediated FAO by inducing autophagy-dependent STAT6 degradation both in TGF-β1-treated HK2 cells and in unilateral ureteral occlusion (UUO) and ischemia–reperfusion (I/R) renal fibrosis mouse models." (PMID 36685533, 2022). "Thus, the role of SQSTM1 in regulating the protective effects of Cana in renal fibrosis may be either dependent or independent of the autophagy pathways." (PMID 36685533, 2022).
vitiligo (3 papers, 2021 to 2023). Generalized well circumscribed patches of leukoderma that are generally distributed over symmetric body locations and is due to autoimmune destruction of melanocytes. "Lower microtubule-associated protein 1 light chain (LC3) II/LC3I ratio and higher sequestosome 1 (SQSTM1, p62) expression were found in vitiligo lesions." (PMID 35406685, 2022). "We demonstrated that, although Atg5 and Atg8 mRNAs were not upmodulated, vitiligo fibroblasts showed a tendency to exhibit elevated autophagy, as assessed by increases of Atg7 gene expression, LC3, and Beclin I production concurrently with the down-modulation of SQSTM1/p62." (PMID 33767135, 2021).
acute lymphoblastic leukemia (2 papers, 2022 to 2023). Leukemia with an acute onset, characterized by the presence of lymphoblasts in the bone marrow and the peripheral blood. "Furthermore, despite no direct links have been so far established between NUP214 and autophagy, a fusion involving NUP214 and the sequestosome-1 (SQSTM1) protein, which is required for proper autophagy induction, has been connected with acute lymphoblastic leukemia." (PMID 37535687, 2023).
acute myeloid leukemia (2 papers, 2022 to 2024). Acute myeloid leukemia (AML) is a group of neoplasms arising from precursor cells committed to the myeloid cell-line differentiation. "The risk score for the acute myeloid leukemia TCGA cohort was calculated as follows: risk score = (0.4655 × SQSTM1 expression) + (−0.2004 × GABARAPL1 expression)." (PMID 36292980, 2022). "Because it may interact with signaling proteins, the autophagy adaptor protein p62/SQSTM1 serves as a hub for signaling and represents an adaptive survival strategy in adult acute myeloid leukemia cells." (PMID 38398467, 2024).
acute pancreatitis (2 papers, 2022 to 2025). An acute inflammatory process that leads to necrosis of the pancreatic parenchyma. "Studies have found that autophagy is involved in the evolution of acute pancreatitis, and Sqstm1/p62 is an important regulator of the autophagy process." (PMID 36671463, 2022).
adenoma (2 papers, 2022). A neoplasm arising from the epithelium. "Accumulated SQSTM1/p62 then traps Keap1, a negative regulator of NRF2, and releases NRF2 from Keap1-mediated regulation, leading to the NRF2 signaling activation and enhancing adenoma formation in the liver." (PMID 36139512, 2022).
And Gaze Palsy (2 papers, 2020 to 2022). "SQSTM1 mutation is a rare cause of neurodegenerative disease characterized by progressive ataxia movement disorders and gaze palsy." (PMID 33135846, 2020).
benign prostate hyperplasia (2 papers, 2015 to 2022). "In benign prostate hyperplasia SQSTM1 positive staining was observed in 8/12 cases (66.7 %) of cases; the proportion of the cells stained was between 10 and 50 %, usually with a weak intensity." (PMID 26423274, 2015). "It has been shown that the increased expression of AMBRA1 in PCa has a significant correlation with Gleason score, and the expression of AMBRA1 and SQSTM1 mRNA is significantly upregulated in PCa samples compared to benign prostatic hyperplasia, which may potentially contribute to PCa progression." (PMID 36361635, 2022).
bone metabolism disorders (2 papers, 2015 to 2021). "Moreover, the potential role of 58 for the treatment of bone metabolism disorders could be explored through in-depth study of the role of p62/SQSTM1 in autophagy." (PMID 34737693, 2021).
brain injury (2 papers, 2017 to 2019). Acute and chronic (see also brain INJURIES, CHRONIC) injuries to the brain, including the cerebral hemispheres, CEREBELLUM, and brain STEM. "Following brain trauma SQSTM1−/− mice show decreased Bag3 mRNA expression levels 5 days after trauma." (PMID 29311767, 2017).
breast tumor (2 papers, 2022 to 2024). "Moreover, the knockdown of TRPV2 in xenograft breast tumors led to the suppression of autophagy, as evidenced by evaluated SQSTM1 levels and decreased expression of ATG5 and LC3." (PMID 39334351, 2024). "To elucidate the biological functions of SQSTM1, GDF9, LINC01125, PTGS2, GVINP1, and TMEM64 in breast tumor cells, we knocked down the expression of the 6-gene signature using shRNA or the negative control in MCF-7 cell lines to assess cell proliferation, migration and invasion in vitro." (PMID 35436939, 2022).
cardiac hypertrophy (2 papers, 2020 to 2025). "Moreover, we found that the expression of other key autophagy-related genes such as ULK1, Atg12, and Atg4B, was significantly upregulated at the protein level in the left ventricle of rats with exercise-induced myocardial hypertrophy, whereas SQSTM1 (a marker of reduced autophagy) was downregulated." (PMID 32140172, 2020).
chronic myelogenous leukaemia (2 papers, 2014 to 2021). "Resveratrol also induced autophagy in imatinib-sensitive (IM-S) and resistant (IM-R) chronic myelogenous leukaemia (K562) cells via JNK-mediated p62/SQSTM1 expression and AMPK activation." (PMID 33802972, 2021).
dyslipidemia (2 papers, 2018 to 2024). "What is the underlying factor responsible for alterations in markers associated with glucose dysmetabolism (GLP-1R), dyslipidemia (LDLRAP1), ferroptosis (NFE2L2), and autophagy (SQSTM1)?" (PMID 38915346, 2024).
epilepsy (2 papers, 2024 to 2025). A brain disorder characterized by episodes of abnormally increased neuronal discharge resulting in transient episodes of sensory or motor neurological dysfunction, or psychic dysfunction. "The expression levels of SQSTM1 and VEGFA in epilepsy model samples were significantly higher than those in normal control, while BNIP and WIPI2 expression levels were notably decreased." (PMID 40217519, 2024). "The results indicated that SQSTM1 and VEGFA exhibited significantly higher expression levels in epilepsy rats compared to the control group." (PMID 40217519, 2024). "We found that SQSTM1 and VEGFA were significantly upregulated, while BNIP and WIPI2 were significantly downregulated in epilepsy model." (PMID 40217519, 2024).
hypertensive disorder (2 papers, 2020 to 2024). Persistently high systemic arterial blood pressure. "In a placenta-specific Atg7 KO mouse, which shows pregnancy-specific hypertension symptoms, an increase in SQSTM1 was observed in parietal trophoblast giant cells and the spongiotrophoblast layer of the placenta." (PMID 39628569, 2024). "Autophagy activation was confirmed by Western blot when researchers observed increases in MAP1LC3-II and decreases in sequestosome 1/p62 (p62) expression in placentas from patients with hypertensive disorder, and the presence of autophagic vacuoles in the syncytial layer of preeclamptic placentas." (PMID 32392703, 2020).
lymph node metastasis (2 papers, 2016 to 2023). "Instead, only a decreased expression of SQSTM1 (p = 0.006), TFEB (p = 0.011), and PRKAA1 (p = 0.001) could be observed in patients with lymph-node metastases (n = 17)." (PMID 36835048, 2023).
myeloid leukemia (2 papers, 2021 to 2025). A clonal proliferation of myeloid cells and their precursors in the bone marrow, peripheral blood, and spleen. "Mutations in SQSTM1/p62 are believed to impact mitophagy and myeloid leukemia development." (PMID 40066097, 2025). "Myeloid leukemia cells transfected with miR-15a-5p inhibitor revealed increased amounts of LC3-II and LAMP-2 detected by Western blotting and immunofluorescence and a decreased protein level of p62/SQSTM1 relative to the scrambled condition." (PMID 34068078, 2021).
myofibrillar myopathy (2 papers, 2018). "Myofibrillar myopathy (MFM) is also caused by aggregation-prone mutations in proteins associated with the Z-disc, including αB-crystallin, SQSTM1, and BAG3, which interact with HSPB8 to mediate chaperone-assisted-selective autophagy (CASA), a process required for the maintenance of myofibrils." (PMID 28780615, 2018).
ovarian tumor (2 papers, 2021). "Increased LC3 and SQSTM1/p62 levels were observed in Z-FY-DMK-treated SKOV3-CTSLP8-OE ovarian tumor tissues." (PMID 33933142, 2021). "Reduced LC3 and SQSTM1/p62 were observed in SKOV3-CTSLP8-OE ovarian tumor tissues." (PMID 33933142, 2021). "In line with the results of the IHC, the protein expression levels of SHH‐F (precursor of the active SHH protein), SHH‐N, and SQSTM1 were dramatically increased in EOC tissues, compared to benign ovarian tumor tissues." (PMID 34076346, 2021).
pancreatic ductal adenocarcinoma (2 papers, 2024). An infiltrating adenocarcinoma that arises from the epithelial cells of the pancreas. "In addition, DDX3X has been shown to promote sequestosome 1 (SQSTM1/p62) accumulation in pancreatic ductal adenocarcinoma, suggesting a regulatory relationship between DDX3X and SQSTM1." (PMID 38265972, 2024). "Reportedly, DDX3X induces epithelial-mesenchymal transition in pancreatic ductal adenocarcinoma by promoting SQSTM1 accumulation, indicating the interaction between DDX3X and SQSTM1." (PMID 38265972, 2024). "In pancreatic ductal adenocarcinoma, CPEB1 serves as a key ferroptosis regulator whose silence promotes the translation of p62/SQSTM1 and NRF2 stability, thus leading to the activation of anti-ferroptosis genes." (PMID 39329964, 2024).
synucleinopathies (2 papers, 2016 to 2022). "In the study reviewed here, we demonstrated that S-nitrosylation of SQSTM1/p62 inhibits autophagic flux, promoting the spread and propagation of synucleinopathy under pathophysiologically-relevant conditions." (PMID 38098743, 2022).
systemic lupus erythematosus (2 papers, 2019 to 2025). An autoimmune multi-organ disease typically associated with vasculopathy and autoantibody production. "Compounds which elevate SQSTM1/p62 levels, like rapamycin and trehalose, are being therefore studied in several phase II and III trials in connection with diabetes mellitus, systemic lupus erythematosus, and autosomal dominant polycystic kidney disease." (PMID 31396308, 2019).
tongue squamous cell carcinoma (2 papers, 2021 to 2022). A squamous cell carcinoma that arises from the tongue. "Dihydroartemisinin decreased P62/SQSTM1 to induce autophagy-mediated death of tongue squamous cell carcinoma." (PMID 36700235, 2022). "The resulting protein expression levels of EGFR and SQSTM1 in tumor tissue of all OSCC patients including buccal mucosa squamous cell carcinoma (BMSCC) and tongue squamous cell carcinoma (TSCC) patients were significantly higher than those in the CTAN tissues (all p < 0.001)." (PMID 34830108, 2021).
triple-negative breast carcinoma (2 papers, 2017 to 2019). An invasive breast carcinoma which is negative for expression of estrogen receptor (ER), progesterone receptor (PR), and human epidermal growth factor receptor 2 (HER2). "In TCGA data set, the gene expression of BECN1, ATG16L1 or SQSTM1 were markedly lower in triple-negative breast cancers (n=82) compared with other subtypes (n=391)." (PMID 28628113, 2017). "Immunohistochemical staining of consecutive sections of triple-negative breast cancer specimens revealed that tumor tissues expressed lower levels of BECN1, ATG16L1 and SQSTM1 than normal tissues." (PMID 28628113, 2017).
(HCMV) infection (1 paper, 2024). "Here, we addressed the question of how the autophagy receptor sequestome 1 (SQSTM1/p62, hereafter referred to as p62) interferes with human cytomegalovirus (HCMV) infection." (PMID 39339916, 2024). "Concordant with the assumption, significantly higher levels of both proteins were detected after the HCMV infection of HFF ko-SQSTM1 at 1 d.p.i. and 2 d.p.i. compared to infected wt cells." (PMID 39339916, 2024). "The induction of ISGs Mx1 and ISG15 was markedly enhanced following HCMV infection of HFF ko-SQSTM1 cells compared to controls." (PMID 39339916, 2024).
acute monocytic leukemia (1 paper, 2022). Acute monoblastic leukemia (AML-M5), is one of the most common subtypes of acute myeloid leukemia (AML) that is either comprised of more than 80% of monoblasts (AML-M5a) or 30-80% monoblasts with (pro)monocytic differentiation (AML-M5b). "After DNA stimulation, SQSTM1 strongly localizes to the same region as STING in human acute monocytic leukemia cells and then mediates autophagic degradation of STING." (PMID 35259065, 2022). "Previous studies have shown that late-stage STING vesicles are sorted to lysosomes for trafficking-mediated STING degradation and that the autophagic cargo receptor SQSTM1 mediates the autophagic degradation of STING in human acute monocytic leukemia cells under HSV-1 stimulation." (PMID 35259065, 2022).
adrenocortical carcinoma (1 paper, 2022). "The risk score for the adrenocortical carcinoma TCGA cohort was calculated as follows: risk score = (−0.622 × SQSTM1 expression) + (0.8342 × ATG9A expression)." (PMID 36292980, 2022).
alcoholic steatohepatitis (1 paper, 2021). "Ubiquitinated KRT18, KRT8, and sequestosome 1/p62 are the main components of Mallory–Denk bodies (MDB) specific for alcoholic steatohepatitis and NASH." (PMID 34063343, 2021).
allergic disease (1 paper, 2023). An immune response that occurs following re-exposure to an innocuous antigen, and that requires the presence of existing antibodies against that antigen. "Recent studies have also verified that PGD regulates glutathione metabolism and SQSTM1 affects autophagy in allergic diseases." (PMID 37328853, 2023).
amyloid (1 paper, 2023). "The enhanced protein level of LC3B-II and reduced SQSTM1 in the brain of 5xFAD mice injected with Fe65-EXO-Cory-B established its ability to augment autophagy, leading to the decreased level of APP-CTF, Aβ and amyloid plaque in the brain of 5xFAD mice." (PMID 37867176, 2023).
Aortic dissection (1 paper, 2020). Aortic dissection refers to a tear in the intimal layer of the aorta causing a separation between the intima and the medial layers of the aorta. "Overall, these findings suggest that EHMT2 functions as a crucial negative regulator of ACD via decreasing SQSTM1 or BECN1 expression and that EHMT2 could be a potent therapeutic target for cardiovascular diseases (e.g., aortic dissection)." (PMID 32174799, 2020).
apraxia (1 paper, 2025). Apraxia is a neurological disorder characterized by the inability to perform tasks or movements, despite having the desire and physical ability to perform them. "In SQSTM1, VCP, and ANXA11 mutations, language impairment appears more variable, with some patients exhibiting speech apraxia or grammatical issues." (PMID 40649976, 2025).